SPRR1B (small proline rich protein 1B)
Description:
Cross-linked envelope protein of keratinocytes. It is a keratinocyte protein that first appears in the cell cytosol, but ultimately becomes cross-linked to membrane proteins by transglutaminase. All that results in the formation of an insoluble envelope beneath the plasma membrane. Can function as both amine donor and acceptor in transglutaminase-mediated cross-linkage.
Synonyms: SPR-IB; GADD33; CORNIFIN; SPRR1
Tractability: Antibody: its Gene Ontology location is reachable by antibodies, with high confidence.
Gene: Protein-coding gene on chromosome 1 (153,031,203 to 153,032,900, forward strand). Ensembl gene ENSG00000169469.
Subcellular location: Cytoplasm
Pathways (Reactome):
Developmental Biology: Formation of the cornified envelope
Gene Ontology:
Molecular function: structural molecule activity
Biological process: keratinocyte differentiation; peptide cross-linking; epidermis development
Cellular component: cornified envelope; cytoplasm; cytosol
Genetic constraint (gnomAD): Loss-of-function variants: 2 observed, 2.19 expected, observed/expected ratio (o/e) 0.91, 90% interval 0.34 to 1.86. That is too few expected variants to judge how well the gene tolerates losing a copy. Missense variants: 102 observed, 109.35 expected, observed/expected ratio (o/e) 0.93, 90% interval 0.79 to 1.1. Synonymous variants: 37 observed, 38.98 expected, observed/expected ratio (o/e) 0.95, 90% interval 0.73 to 1.25.
Homologues: Orthologues: pig SPRP (90% identical). Paralogues in human: SPRR1A (96% identical), SPRR3 (75% identical), SPRR4 (52% identical), SPRR2G (43% identical), KPLCE (31% identical), PRR9 (31% identical), LCE2B (27% identical), LCE2C (27% identical), LCE2D (27% identical), LCE1E (26% identical), LCE1F (26% identical), LCE2A (26% identical), and 8 more.